TAC1 (tachykinin precursor 1)
Description:
Tachykinins are active peptides which excite neurons, evoke behavioral responses, are potent vasodilators and secretagogues, and contract (directly or indirectly) many smooth muscles. [Substance P]: Is a ligand for TACR1, and triggers G protein-coupled receptor signaling via activation of phosphatidylinositol hydrolysis by phospholipase C. Substance P binding to TACR1 also triggers signaling via activation of adenylate cyclase activity which results in increased intracellular levels of cyclic AMP (cAMP) (By similarity). Is also a TACR3 agonist with low receptor affinity. Basic secretagogue neuropeptide released from the terminals of specific sensory nerves. Acts as a ligand for MRGPRX2 receptor in mast cells, initiating a signaling that mediates neurogenic inflammation and pain. Neurogenic inflammation includes mast cell activation, recruitment of immune cells and release of inflammatory mediators, such as cytokines and chemokines (By similarity). The inflammatory response can then activate or sensitize nociceptors, promoting pain (By similarity). [Neurokinin A]: Is a ligand for TACR2, and triggers G protein-coupled receptor signaling via activation of G(q) and phosphatidylinositol hydrolysis by phospholipase C. Binding to TACR2 also triggers signaling via activation of adenylate cyclase activity which results in increased intracellular levels of cyclic AMP (cAMP).
Synonyms: NPK; NKNA; TAC2; Hs.2563; NK2
Tractability: Small molecule: a structure with a bound ligand is known. Antibody: its Gene Ontology location is reachable by antibodies, with high confidence; UniProt places it where antibodies can reach, with medium confidence; UniProt predicts a signal peptide or a membrane-spanning region.
Gene: Protein-coding gene on chromosome 7 (97,732,053 to 97,740,472, forward strand). Ensembl gene ENSG00000006128.
Subcellular location: Secreted; Secreted (Substance P)
Pathways (Reactome):
Signal Transduction: G alpha (q) signalling events; Tachykinin receptors bind tachykinins
Gene Ontology:
Molecular function: substance P receptor binding
Biological process: positive regulation of cytosolic calcium ion concentration; cell-cell signaling; detection of abiotic stimulus; inflammatory response; insemination; tachykinin receptor signaling pathway; adenylate cyclase-activating G protein-coupled receptor signaling pathway; associative learning; long-term memory; negative regulation of heart rate; phospholipase C-activating tachykinin receptor signaling pathway; positive regulation of action potential; positive regulation of acute inflammatory response; positive regulation of corticosterone secretion; positive regulation of epithelial cell migration; positive regulation of lymphocyte proliferation; positive regulation of ossification; positive regulation of stress fiber assembly; positive regulation of synaptic transmission, cholinergic; positive regulation of synaptic transmission, GABAergic; regulation of blood pressure; response to hormone; response to lipopolysaccharide
Cellular component: extracellular region; neuronal dense core vesicle
Genetic constraint (gnomAD): Loss-of-function variants: 6 observed, 14.55 expected, observed/expected ratio (o/e) 0.41, 90% interval 0.22 to 0.81. The upper end of that interval is the gene's LOEUF score, 0.81, which puts it in group 3 of 6, group 1 being the genes least tolerant of losing a copy. Missense variants: 92 observed, 109.2 expected, observed/expected ratio (o/e) 0.84, 90% interval 0.71 to 1. Synonymous variants: 41 observed, 41.87 expected, observed/expected ratio (o/e) 0.98, 90% interval 0.76 to 1.27.
Homologues: Orthologues: pig TAC1 (99% identical), rat Tac1 (97% identical), guinea pig TAC1 (95% identical), mouse Tac1 (95% identical), chimpanzee TAC1 (90% identical), dog TAC1 (88% identical), macaque TAC1 (74% identical), rabbit TAC1 (72% identical), tropical clawed frog tac1 (53% identical), zebrafish tac1 (41% identical), zebrafish tac4 (23% identical).
Diseases named in the same sentence as TAC1 in open-access papers:
TAC1 is named in the same sentence as 363 diseases in open-access papers, as found by Europe PMC text mining. Sharing a sentence is not in itself a finding about the gene and the disease. The quoted sentences say what the papers report.
Anxiety (48 papers, 2010 to 2026). Intense feelings of nervousness, tension, or panic often arise in response to interpersonal stresses. "Expression or introduction of the neuropeptide substance-P (SP; encoded by the TAC1 gene in humans and Tac1 in rodents) in the amygdala induces anxiety related behaviour in rodents." (PMID 25001955, 2014). "Here we report that Tachykinin Precursor 1 (Tac1)-expressing neurons in the medial amygdala (MeA) respond to the transition from high anxiety to low anxiety states." (PMID 40721553, 2025). "During the exploration of the elevated plus maze, when the mice move from the open arms to the closed arms, leading to a decrease in anxiety levels, the activity of Tac1 neurons increases concurrently." (PMID 40721553, 2025). "Subsequently, we sought to identify the upstream brain regions with inputs to Tac1 neurons that are potentially involved in regulating anxiety-like behaviors in mice." (PMID 40721553, 2025). "Our findings reveal a circuit of Tac1 neurons in the MeA that mediates anxiety-like behaviors in mice." (PMID 40721553, 2025). "The deletion of the TAC1 gene results in decreased anxiety-like and depression-like behaviors in mice." (PMID 36004833, 2022). "Substance P (SP), a neuropeptide that, along with the less well characterised neurokinin-A (NKA), is encoded by the human TAC1 gene (Tac1 in rodents) and is expressed in both the medial and central amygdala where it modulates anxiety levels." (PMID 25001955, 2014). "The identification of Dex/forskolin response elements in the TAC1 promoter in amygdala neurones suggests a possible link in the chain of molecular events connecting GR activation and anxiety." (PMID 25001955, 2014). "As previous work demonstrates, this suggests that Tac1 neurons in the MeA may play an important role in regulating anxiety-like behavior in mice." (PMID 40721553, 2025). "However, the more recent evolution of SNPGR may have allowed a tempering of the GR response of TAC1prom in higher primates possibly serving to reduce the effects of stress hormones on the expression of TAC1 and reducing levels of anxiety in these animals." (PMID 25001955, 2014). "Stressful stimuli increase levels of SP and Tac1 mRNA within the amygdala regions of restrained rodents an observation reminiscent of patients diagnosed with stress disorders or those placed in anxiety inducing situations who have elevated levels of SP in their cerebral spinal fluid." (PMID 25001955, 2014). "The results of the anxiety behavioral assays revealed that Tac1 knockdown in the MeA failed to induce anxiety-like behaviors in the mice (Fig. EV6C–H)." (PMID 40721553, 2025). "In this study, we found that although Tac1 neurons secrete both substance P and GABA, substance P does not affect anxiety-like behavior in mice." (PMID 40721553, 2025).
depression (48 papers, 2008 to 2026). "Our results show a significant upregulation of MAOA and TAC1 in the medial area frontopolaris which is a node in the limbic-cortical network and known to be susceptible for gray matter loss and behavioral dysfunction in patients with depression." (PMID 29478144, 2018). "Substance P is cleaved from preprotachykinin A (PPTA) encoded by Tac1, which plays a neurotransmitter or neuroregulatory role in central and peripheral nervous systems and is involved in a variety of physiological and disease processes, including vomiting, nociception, inflammation and depression." (PMID 31768887, 2020). "In models of depression-related behavior, mice with a homozygous deletion of tac1 (tac1−/−) were more active than wildtype mice, i.e., they behaved like wildtype mice under medication with an antidepressant, as reviewed by Bilkei-Gorzo and Zimmer (2005)." (PMID 29478144, 2018). "The list includes several genes previously implicated in depression including the NTRK2, AXL and TAC1 genes." (PMID 25734512, 2015). "GWAS for the HGA/GR ratio identified two genetic loci that mapped to the TAC1 and ASNS genes, which are known to be involved in depression and neurotransmission, while the ratio MET/TYR identified the gene AGBL1 previously linked to neurodegeneration in mice." (PMID 31273200, 2019). "Notably, their increased activity in depression-related paradigms, such as the forced-swimming test and the tail suspension test, as well as their lack of hyperactivity after bullectomy, can primarily be attributed to the TAC1 gene’s specific binding to substance P." (PMID 38510807, 2024).
asthma (40 papers, 2002 to 2026). "Patients in OAC3 represent those with severe eosinophilic T2 asthma and have a similar comparative enrichment of the Woodruff signature between the eosinophilic TAC1 and the neutrophilic/inflammasome‐containing TAC2 subjects." (PMID 39073027, 2024). "TAC1 was distinguished by a predominant Th2 signature, including elevated expression of interleukin (IL)-33, innate lymphoid cells (ILC) type 2, and IL-13 genes, and was associated with eosinophilic airway inflammation and severe asthma." (PMID 41590536, 2026). "In the U-BIOPRED clinical data, TAC2 was associated with a lesser extent of chronic airflow obstruction compared with that in TAC1; however, a mixed inflammatory nature is becoming increasingly known as a biomarker of the most severe form of asthma." (PMID 30736433, 2019). "A transcriptomic analysis of sputum samples after 1 year showed that severe asthma molecular phenotypes were unstable in about half of patients, with many shifting from TAC1 or TAC3 to TAC2." (PMID 41590536, 2026). "Researchers tracked U-BIOPRED severe asthma patients for a year and found that 55% maintained stable endotypes (TACs), while 45% changed, mainly from TAC1 or TAC3 to TAC2." (PMID 41303221, 2025).
breast carcinoma (28 papers, 2003 to 2025). "Hypermethylation of TAC1 is associated with poor prognosis in esophageal cancer, breast cancer, and colorectal cancer." (PMID 29682090, 2018). "The set of selected genes was composed of a group of angiogenesis-related genes (VEGF, PDGF, ANG-1, and PF-4) and genes that have been previously associated with carcinogenic or metastatic processes in breast cancer (WASF3, LAPTM4B, TPM3, and TAC1)." (PMID 37176055, 2023). "According to the present results, TAC1 showed variations in mRNA levels in platelet samples from breast cancer patients compared to tumor tissue samples." (PMID 37176055, 2023). "Hinterleitner concluded that the expression of TAC1 in platelets has potential as a biomarker in liquid biopsies for breast cancer." (PMID 37176055, 2023). "In the four molecular subtypes, the TAC1 gene exclusively had variation in mRNA levels in platelets from patients with breast cancer." (PMID 37176055, 2023). "The TAC1 gene was the one that allowed us to differentiate between a healthy sample and a breast cancer sample." (PMID 37176055, 2023). "Secretion of chemokine (C-C motif) ligand type 5 by MSCs was shown to be critical for metastasis in breast cancer, and MSCs support the entry of breast cancer into the BM through Tac1 regulation." (PMID 30705410, 2019). "Tac1 expression in the breast cancer cell lines was found to play a key role in bone marrow EC transmigration and the adherence of the metastatic cells to MSCs through the regulation of CXCR4 and SDF-1α production in the breast cancer cells." (PMID 28148268, 2017). "Hypermethylation of TAC1 has been described in esophageal cancer, gastric cancer, colon cancer, and breast cancer." (PMID 25734919, 2015). "Luciferase assay results indicate that Tac1, which confers a poor prognosis in breast cancer, was the directly correlated to miR-137." (PMID 26215676, 2015). "Tac1 has been linked to breast cancer (BC) development, and invasion into bone marrow (BM) (." (PMID 18575622, 2008). "In our work, the PCA showed that the TAC1 gene could differentiate healthy samples from breast cancer samples." (PMID 37176055, 2023). "In 2021, Hinterleitner studied the expression levels of TAC1 mRNA in breast cancer patients." (PMID 37176055, 2023). "Hypermethylation of TAC1 has been described in esophageal, gastric, colon, and breast cancer." (PMID 27027429, 2016). "Moreover, luciferase assay results indicate that Tac1, which confers a poor prognosis in breast cancer, was the direct target of miR-137." (PMID 26215676, 2015). "For example, Tac1, the gene encoding Tachykinin-1, the precursor protein for neuroendocrine peptides, is expressed in the mammary mesenchyme during embryonic development and the level of Tac1 expression in breast cancers is directly proportional to their aggressiveness." (PMID 26215676, 2015). "Such treatments could bepossible in the near future due to the availability of CXCR4 antagonists.In summary, we propose that Tac1 contributes to breast cancer cell metastasis and integration into bone marrowstromal compartment." (PMID 19277104, 2008). "Additionally, Tac1 manages the transition of breast cancer cells into a quiescent phenotype in themarrow cavity." (PMID 19277104, 2008). "Finally, SMCX was found in a protein complex with REST, which represses transcription of neuronal genes in non-neuronal tissues, and was recently found to play a tumor suppressor role in breast cancer by suppression of the oncogenic TAC1 (tachykinin, precursor 1) protein." (PMID 21996408, 2011). "Thus, miRNAs against Tac1 may affect quiescence of breast cancer cells in the marrowcavity." (PMID 19277104, 2008).
Pruritus (20 papers, 2014 to 2026). Pruritus is an itch or a sensation that makes a person want to scratch. "This study investigates the role of paired‐like homeobox 2a (Phox2a) in tachykinin 1‐positive (Tac1+) neurons of the lateral spinal nucleus (LSN) as a novel target for histamine‐independent pruritus intervention." (PMID 41204431, 2025). "In Tac1‐Ai9 mice, quantitative analyses revealed that 16.39% ± 6.78% of Tac1‐positive neurons showed c‐FOS/Tac1 double‐labeling following His‐induced itch, compared to 34.46% ± 5.18% in CQ‐induced acute itch models." (PMID 41204431, 2025). "Our previous findings demonstrated the effects of modulations of the LSNPhox2a neurons in CQ‐induced itch, leading us to investigate whether this regulatory effect specifically occurred in Tac1‐positive neurons." (PMID 41204431, 2025). "Pruritogens, including TAC1, IL-2, IL-31, TPSAB1, TPSB2, and TPSG1, and the key enzymes that are attributed to itch, including HDC and TPH1, were detected by RNA-seq." (PMID 35632808, 2022).
glioma (19 papers, 1999 to 2026). A benign or malignant brain and spinal cord tumor that arises from glial cells (astrocytes, oligodendrocytes, ependymal cells). "It has also been demonstrated that the NK-1R is necessary for the survival of human GAMG and U87 MG glioma cells, but the expression of the TAC1 gene is not needed for the viability of these cells." (PMID 35434136, 2022). "It has been also shown that the TAC1 gene expression is not relevant for the viability of GAMG glioma cells." (PMID 35434136, 2022). "We have also demonstrated that the TAC1 silencing by siRNA did not produce any change in GAMG glioma cells and, hence, the absence of SP synthesis in these cells did not affect their survival." (PMID 35434136, 2022). "By contrast, the silencing of TAC1 expression by TAC1 siRNA did not produce any change in cell proliferation in GAMG glioma cells (data not shown)." (PMID 35434136, 2022).
lung carcinoma (19 papers, 2010 to 2026). "Collectively, this study reveals that the methylation of 7 genes (TAC1, CDO1, HOXA9, ZFP42, SOX17, RASSF1A and SHOX2) has a big significance in the diagnosis of lung cancer and achieved a diagnostic model with high sensitivity and specificity." (PMID 38315228, 2024). "For lung cancer risk prediction, univariate logistic regression analysis revealed that methylation levels of SOX17, HOXA9, CDO1, and TAC1 were significantly related to lung cancer risk." (PMID 36153611, 2022). "As elevated odds ratios ranged from 2.81 to 7.19, logistic regressions analyses also indicated that the methylation of CDO1, TAC1, SOX17, and HOXA7 were closely related to increasing lung cancer risk." (PMID 32138766, 2020). "An epigenetic classifier including four genes (HOXA9, RASSF1A, SOX17, and TAC1) that was evaluated in sputum by ddPCR reached an AUROC of 0.92 for lung cancer detection." (PMID 31817025, 2019). "Four genes (HOXA9, RASSF1A, SOX17, and TAC1) were identified as the best biomarkers (all p < 0.001) and incorporated into a logistic classifier: Probability of lung cancer = ex/(1 + ex), where x = 1.69 + 1.48 × log (HOXA9) − 1.25 × log (RASSF1A) + 0.27 × log (SOX17) + 0.16 × log (TAC1)." (PMID 29796119, 2018). "Methylation analysis in the plasma DNA of certain genes (SOX17, TAC1, HOXA7, SOX17, HOXA9 ZFP42h) using quantitative methylation-specific real-time PCR and methylation-on-beads for cancer-specific genes showed a strong association with the diagnosis of early-stage lung carcinoma." (PMID 30917582, 2019). "Then, we explored the diagnosis value of the DNA methylation status of 7 genes including TAC1, CDO1, HOXA9, ZFP42, SOX17, RASSF1A and SHOX2 in lung cancer." (PMID 38315228, 2024). "To this end, we compared the DNA methylation status of 7 genes including TAC1, CDO1, HOXA9, ZFP42, SOX17, RASSF1A and SHOX2 in lung cancer cases with different stages." (PMID 38315228, 2024). "Here, we compared the DNA methylation status of 7 genes including TAC1, CDO1, HOXA9, ZFP42, SOX17, RASSF1A and SHOX2 in lung cancer cases with I–IV stages." (PMID 38315228, 2024). "Here, we explored the significance of the DNA methylation of 7 genes including TAC1, CDO1, HOXA9, ZFP42, SOX17, RASSF1A and SHOX2 in the blood cfDNA samples in distinguishing lung cancer from benign nodules and healthy individuals." (PMID 38315228, 2024). "In this study, we explored the significance of the DNA methylation of 7 genes including TAC1, CDO1, HOXA9, ZFP42, SOX17, RASSF1A and SHOX2 in the blood cfDNA samples in distinguishing lung cancer from benign nodules and healthy individuals." (PMID 38315228, 2024). "Promoter methylation of eight lung cancer-specific genes (CDO1, TAC1, SOX17, HOXA7, HOXA9, GATA4, GATA5, and PAX5) was detected using nanoparticle-based DNA extraction (MOB) followed by qMSP." (PMID 32138766, 2020). "In conclusion, despite these limitations, our meta-analysis advocates that methylated SOX17, CDO1, ZFP42, TAC1, FAM19A4, FHIT, MGMT, p16, and RASSF1A are useful biomarkers in the screening and auxiliary detection of lung cancer." (PMID 28644424, 2017). "While many biomarkers have been shown to be viable for gastric and urinary cancers such as bladder and CRC, one study also reported a successful DNA methylation analysis (1.7) of a panel (CDO1, TAC1, HOXA7, HOXA9, SOX17, and ZFP42 promoters) to diagnose lung cancer." (PMID 40141826, 2025). "Moreover, we compared the DNA methylation status of 7 genes (TAC1, CDO1, HOXA9, ZFP42, SOX17, RASSF1A and SHOX2) in lung cancer cases from the mass and GGNs groups." (PMID 38315228, 2024). "Following a large literature review, we explored the performance of the DNA methylation of 7 genes including TAC1, CDO1, HOXA9, ZFP42, SOX17, RASSF1A and SHOX2 in the blood cfDNA samples in distinguishing lung cancer from benign nodules and healthy individuals." (PMID 38315228, 2024).
lung carcinoma (continued). "Therefore, we advocate that methylated SOX17, CDO1, ZFP42, TAC1, FAM19A4, FHIT, MGMT, p16, and RASSF1A are useful in the screening and auxiliary detection of lung cancer." (PMID 28644424, 2017). "This confirmed the utility of CDO1, TAC1, HOXA7, and SOX17, while newly tested genes were not as effective for lung cancer detection." (PMID 32138766, 2020).